ESR2 (estrogen receptor 2)
Diseases named in the same sentence as ESR2 in open-access papers (continued):
Sharing a sentence is not in itself a finding about the gene and the disease.
brain tumor (4 papers, 2014 to 2024). "To determine if tumor ER expression, both α (ESR1) and β (ESR2), plays a role in brain tumor protective function, we performed an analysis of gene expression in the GBM dataset." (PMID 38411438, 2024).
breast adenocarcinoma (4 papers, 2010 to 2023). "Therefore, to investigate whether the combined S30 and LGA1, denoted as S30+LGA1, could increase the estrogen level, the mRNA expression of the genes of estrogen receptors, ESR1 and ESR2, and an estrogen-related gene of pS2 in MCF-7 cells from human breast adenocarcinoma cell line, were analyzed." (PMID 37892560, 2023).
cervical tumor (4 papers, 2020 to 2024). "ESR2 was downregulated in breast, ovarian, and cervical tumors only." (PMID 38582811, 2024).
colon adenocarcinoma (4 papers, 2011 to 2025). "A lack of ESR2 expression in human colon adenocarcinoma has been reported, suggesting that ESR2 might be a tumour suppressor." (PMID 25376484, 2014).
colorectal tumor (4 papers, 2017 to 2023). "Consistent with the results of the in vitro cell experiments, it was found that ISL can suppress the growth of colorectal tumours and regulate the ESR2 and PI3K/AKT pathways in vivo." (PMID 38256877, 2023).
COVID-19 (4 papers, 2021 to 2025). A disease caused by infection with severe acute respiratory syndrome coronavirus 2. "Moreover, medications boosting the down-stream signaling of ESR1/ESR2, or inhibiting the inflammation and immune-associated targets on the signaling network can be potentially effective or synergistic combined with other existing drugs for COVID-19 treatment." (PMID 35676404, 2022). "All the results indicated that the estrogens, interacting with ESR1/ESR2, are the essential sex factors protecting young female COVID-19 patients." (PMID 35676404, 2022). "Medications perturb the down-stream of ESR1/ESR2 to inhibit the inflammation and immune response can be effective or synergistic combined with other existing drugs for COVID-19 treatment." (PMID 34611658, 2021). "Although estrogen regulation of ACE2 expression has been proposed to mediate the sexual dimorphism of COVID-19 susceptibility, and estrogen receptor binding sites have been identified near the ACE2 locus, we did not detect an effect of ESR1 or ESR2 disruption on ACE2 abundance." (PMID 35231079, 2022).
gallstones (4 papers, 2012 to 2020). Solid crystalline precipitates in the biliary tract, usually formed in the gallbladder, resulting in the condition of cholelithiasis. "In conclusion, our study showed that ESR1 IVS1-397C>T (rs2234693), ESR1 IVS1-351A>G (rs9340799), ESR2 -789 A>C (rs1271572) polymorphisms and their higher-order interactions may confer increased risk of gallbladder carcinoma, probably through gallstone mediated pathway." (PMID 22808109, 2012). "In other study ESR1 polymorphic variants: IVS1-397C > T, ESR1 IVS1-351A > G and ESR2-789 A > C correlated with GBC risk, mediated through gallstone dependent pathway." (PMID 32024900, 2020). "Using multi-analytical approaches, our study showed important role of ESR1 IVS1-397C>T, ESR1 IVS1-351A>G, and ESR2-789 A>C variants in GBC susceptibility and the risk appears to be mediated through gallstone dependent pathway." (PMID 22808109, 2012). "Therefore, in the present study, we investigated a panel of 6 well-studied polymorphisms in ESR1, ESR2 and PGR genes in a case–control design involving 410 GBC patients, 230 gallstone patients and 220 cancer/gallstone-free controls from North India." (PMID 22808109, 2012). "Furthermore, none of the ESR2 haplotypes conferred risk for gallstones presenting the global haplotypes association p-value = 0.65." (PMID 23577061, 2013). "However, the variant-containing genotypes (DI+II) of PGR (rs1042838) showed low risk in both GBC [OR = 0.4] and gallstone patients [OR = 0.4].On performing the MDR analysis, ESR1 IVS1-397C>T, ESR1 IVS1-351A>G, and ESR2-789 A>C yielded the highest testing accuracy of 0.634." (PMID 22808109, 2012). "Furthermore, the ESR1-selective agonist propylpyrazole, but not the ESR2-selective agonist diarylpropionitrile, promotes hepatic cholesterol output, leading to cholesterol-supersaturated bile and gallstones." (PMID 33281743, 2020). "However, none of the ESR2 haplotypes were found to be associated with GBC and gallstone risk." (PMID 22808109, 2012).
male infertility (4 papers, 2005 to 2025). The inability of the male to effect fertilization of an ovum after a specified period of unprotected intercourse. "Association study between polymorphisms of the ESR1 (PvuII and XbaI) and ESR2 (RsaI and Alul) genes and male infertility suggested 3 times higher frequency of the heterozygous RsaI genotype in men with low sperm concentration compared to the controls." (PMID 29766145, 2018).
neuropathy (4 papers, 2016 to 2025). A disorder affecting the nervous system that manifests with pain, tingling, numbness, and/or muscle weakness. "Esr1 and Esr2 are expressed in both IHCs and OHCs, and they protect against neuropathy following acoustic trauma." (PMID 26881968, 2016).
ovarian failure (4 papers, 2019 to 2025). "Other genes like the WNT4, ESR2 and SF-1 have a necessary role for ovarian and testicular development function as demonstrated by the fact that genetic variants in these genes cause gonadal dysgenesis in 46,XY individuals, with ovarian failure in women and ovotesticular DSD42,70,74." (PMID 31745224, 2019).
renal carcinoma (4 papers, 2020 to 2024). A carcinoma arising from the epithelium of the renal parenchyma or the renal pelvis. "In terms of OS, in renal cancers, KICH (p-value = 0.0002), and KIRC (p-value = 0.000001), a low ESR2 expression level was associated with longer OS compared to a high ESR2 expression level for both sexes." (PMID 39201394, 2024).
uterine fibroid (4 papers, 2015 to 2025). "Therefore, the present study hypothesized that variations in the ESR2 gene promoter and exonic regions may potentially cause alterations in its biological function and influence uterine leiomyoma risk." (PMID 31423418, 2019).
chronic kidney disease (3 papers, 2023 to 2025). Impairment of the renal function secondary to chronic kidney damage persisting for three or more months. "In chronic kidney disease (CKD), CNN2 regulates energy metabolism by interacting with estrogen receptor 2 (ESR2) to control fibrosis progression." (PMID 37751293, 2023).
chronic myeloid leukemia (3 papers, 2020 to 2022). "Disruption of the ESR2 gene in mice (ERβ−/−) resulted in hypercellularity of the bone marrow and myeloproliferative neoplasia resembling chronic myeloid leukemia." (PMID 32276421, 2020).
colorectal polyps (3 papers, 2021 to 2024). "Studies have demonstrated that the expression of estrogen receptor β (ERβ/ESR2) is negatively correlated with the presence of colorectal polyps and tumor staging, which can reduce the risk of death in women." (PMID 39634543, 2024). "Loss or mutation in ESR2 is associated with the presence of colorectal polyps, tumor stage, and grade." (PMID 36532007, 2022). "There is evidence that the expression of estrogen receptor β (ERβ/ESR2) is inversely related to the presence of colorectal polyps and tumor stage." (PMID 35083251, 2021).
female infertility (3 papers, 2015 to 2022). Diminished or absent ability of a female to achieve conception. "Specifically, VDR is associated with female infertility, whereas CEBPB has been described as relevant factor for female reproduction for its role in ovarian follicle development, together with SMAD3 and ESR2." (PMID 36589743, 2022).
lung squamous cell carcinoma (3 papers, 2021 to 2024). "Lung squamous cell carcinoma (LUSC) and COAD demonstrated the greatest number of correlations, yielding nine and seven significant outcomes between ESR2 and target genes, respectively." (PMID 39201394, 2024).
melasma (3 papers, 2022 to 2025). "For example, specific Cassipourea metabolites have shown significant binding effects on ESR1 and ESR2, suggesting their potential as modulators in melasma treatment." (PMID 41154805, 2025). "Recent network pharmacology and molecular dynamics studies investigating potential melasma treatments have highlighted the involvement of estrogen receptors (ESR1 and ESR2) and the prolactin signaling pathway in melasma pathogenesis." (PMID 41154805, 2025). "TheWNT3A, EDN3, ESR2, PTG2, MMP1, and SOD2 genes were up-regulated, whereas the COL4A1, CSF2, DKK3, COL7A1, TIMP4, CCL2, and CDH11 genes were down-regulated in melasma skin fibroblasts when compared to the ones from adjacent healthy skin." (PMID 35840442, 2022).
age-related hearing loss (2 papers, 2018 to 2021). "Furthermore, estrogen receptor-β (estrogen receptor 2 or ESR2) knockout (KO) mice of both sexes are more susceptible to TTS-inducing noise exposures than their wildtype littermate controls, while female ESR2 KO mice display early onset age-related hearing loss (ARHL)." (PMID 34830090, 2021).
glaucoma (2 papers, 2013 to 2023). Increased pressure in the eyeball due to obstruction of the outflow of aqueous humor. "This raises questions regarding whether polymorphisms in ESR2 (which codes for the estrogen receptor found on retinal ganglion cells) may alter affinity for estrogen and affect retinal ganglion cell viability in glaucoma." (PMID 23869166, 2013).
Hernia (2 papers, 2009 to 2025). "The ESR2- and GPER1-selective antagonists PHTPP and G-15, respectively, exhibited no discernible effects on hernia size compared with placebo treatment." (PMID 39903526, 2025).
hip fracture (2 papers, 2009 to 2013). Traumatic or pathological injury to the hip in which the continuity of either the femoral head, femoral neck, intertrochanteric or subtrochanteric regions is broken. "Another research detected a significant association of rs960070 in ESR2 with hip fractures in 700 elderly Chinese subjects." (PMID 23894347, 2013).
intrahepatic cholestasis (2 papers, 2022 to 2025). A cholestasis characterized by impairment of the bile flow caused by obstruction located in the liver. "We validated the changes in 5 out of 7 core putative targets in the treatment of DCHT for ANIT-induced intrahepatic cholestasis, with the exception of estrogen receptor (ESR) 1 and 2 (ESR1 and ESR2) because they are more associated with intrahepatic cholestasis during pregnancy." (PMID 35370715, 2022). "Pathogenic prediction for five missense variants of the ESR2, CYP1A2, and CYP17A1 genes in 249 Han Chinese people with intrahepatic cholestasis of pregnancy." (PMID 40933484, 2025).
osteoarthritis (2 papers, 2010 to 2012). A noninflammatory degenerative joint disease occurring chiefly in older persons, characterized by degeneration of the articular cartilage, hypertrophy of bone at the margins and changes in the synovial membrane. "The objective of this study was to examine the relationship between common genetic variation of the ESR2 gene and osteoarthritis." (PMID 21080949, 2010). "This study showed that common genetic variation in the ESR2 gene is not likely to influence the risk of osteoarthritis with effects smaller than a 13% increase." (PMID 21080949, 2010).
ovarian serous cystadenocarcinoma (2 papers, 2021 to 2024). A malignant serous cystic epithelial neoplasm arising from the ovary. "Patient groups with only one sex, cervical squamous cell carcinoma and endocervical adenocarcinoma (CESC) (p-value = 0.004), and ovarian serous cystadenocarcinoma (OV) (p-value = 0.002) (only female samples) presented high ESR2 expression levels as a favorable factor with regard to OS." (PMID 39201394, 2024).
papilloma (2 papers, 2012 to 2020). A benign epithelial neoplasm that projects above the surrounding epithelial surface and consists of villous or arborescent outgrowths of fibrovascular stroma. "Cluster I MIBCs mainly include papilloma pathological phenotypes enriched in FGFR3 gene mutations; Clusters I and II highly express GATA3, FOXA1, UPK3A and luminal and uroplakin genes and are enriched in RBB2 mutations and estrogen receptor beta (ESR2)." (PMID 32117752, 2020).
preeclampsia (2 papers, 2020 to 2021). Preeclampsia is a hypertensive disorder of pregnancy that is characterized by new-onset hypertension with proteinuria presenting after 20 weeks of gestation, and depending on mild or severe forms may initially present with severe headache, visual disturbances, and hyperreflexia. "The expression of ESR1 is reduced in preeclamptic placentas, whereas the placental expression of Erβ-encoding gene ESR2 is upregulated in preeclampsia." (PMID 34445328, 2021).
renal fibrosis (2 papers, 2025). A final common manifestation of a wide variety of chronic kidney diseases characterized by glomerulosclerosis and tubulointerstitial fibrosis. "CNN2 deficiency can upregulate CPT1A and other key enzymes through ESR2-PPARα axis, promote FAO and reduce renal fibrosis after RIRI." (PMID 41451126, 2025).
sarcoma (2 papers, 2017 to 2024). A usually aggressive malignant neoplasm of the soft tissue or bone. "Sarcoma (SARC) patients with simultaneous low expression levels of TNFRSF13C and ESR2 presented longer OS (p-value = 0.034)." (PMID 39201394, 2024).
somatotropinomas (2 papers, 2023 to 2024). "Expression of ESRB is distinctive in gonadotroph and null-cell adenomas, while genes ESR1 and ESR2 are co-expressed in prolactinomas, somatotropinomas, and prolactinomas." (PMID 39022728, 2024).
apical periodontitis (1 paper, 2021). "Recently, the association between polymorphisms in genes encoding estrogen receptors 1 and 2 (ESR1 and ESR2), vitamin D receptor (VDR), and in miRNA-17 with apical periodontitis was reported in the literature." (PMID 33886945, 2021).
Arthralgia (1 paper, 2021). "In addition, Estrogen receptor 1 (ESR1) and ESR2 gene polymorphisms have been linked to treatment-related arthralgia." (PMID 33530456, 2021).
autoimmune myasthenia gravis (1 paper, 2023). "In autoimmune myasthenia gravis, which is more frequent in women than in men, the ESR1 gene expressing estrogen receptor α (ERα) and the ESR2 gene expressing estrogen receptor β (ERβ) can mediate multiple physiological effects of estrogen." (PMID 36818231, 2023).
central obesity (1 paper, 2022). "Here, we observed that ESR2 expression in SAT from females was negatively associated with markers of central obesity such as WHR and VAT volume." (PMID 35856485, 2022). "ESR2 expression was inversely correlated with measures of central obesity and expression of some fatty acid oxidation markers, and positively correlated with lipid storage and glucose transport markers." (PMID 35856485, 2022). "We found that ESR2 expression was negatively correlated with markers of central obesity and positively correlated with markers of lipid storage and glucose metabolism." (PMID 35856485, 2022). "In this study, we show that ESR2 expression in adipose tissue from females is negatively correlated with markers of central obesity and fatty acid oxidation markers, and positively correlated to expression markers of lipogenesis and ex vivo adipocyte glucose uptake." (PMID 35856485, 2022).
colorectal adenocarcinoma (1 paper, 2025). The most common type of colorectal carcinoma. "Integration with machine learning‐selected hub genes identified ESR2 and CDC42 as promising molecular targets potentially underlying tumor and normal tissues differences in colorectal adenocarcinoma." (PMID 41246859, 2025).
cyst (1 paper, 2021). A sac-like closed membranous structure that may be empty or contain fluid or amorphous material. "Phytoestrogens, such as genistein, induce a delay in oocyte cyst breakdown and MOF formation via ESR2." (PMID 33658225, 2021).
dental fluorosis (1 paper, 2025). A condition that results from excessive fluoride ingestion during tooth development, resulting in tooth discoloration ranging from white streaks to brown stains and cracks or pits in the tooth enamel. "Therefore, this study aimed to investigate whether ESR1 rs12154178 and ESR2 rs1256049 polymorphisms are associated with the severity of dental fluorosis in pregnant women from Durango, Mexico." (PMID 41174690, 2025).
facioscapulohumeral muscular dystrophy (1 paper, 2021). An autosomal dominant disorder affecting the skeletal muscles of the face, scapula, and upper arm. "This could be a good resource for DMD, since ESR2 induces muscular differentiation in facioscapulohumeral muscular dystrophy and GSK3b could help to reduce muscular degeneration." (PMID 33918694, 2021).
Follicular Cyst (1 paper, 2023). Cyst due to the occlusion of the duct of a follicle or small gland. "Our data also showed that the mRNA expressions of ESR1, ESR2, PGR, IGF1Rs and GHSR were changed in follicular cysts." (PMID 37958056, 2023).
gallbladder carcinoma (1 paper, 2012). "Therefore the present study was designed to explore the role of genetic variants in estrogen (ESR1, ESR2) and progesterone (PGR) receptors in conferring risk of gallbladder cancer." (PMID 22808109, 2012). "Given the potential hormonal role in gallbladder diseases, and also the previously explored role of ESR/PGR polymorphisms in female related cancers, we hypothesized that genetic variants in ESR1, ESR2 and PGR genes may have significant impact on the risks of gallbladder cancer." (PMID 22808109, 2012).
gynecological cancers (1 paper, 2019). "So far, many studies were conducted on the role of estrogen receptor beta (ESR2) gene polymorphisms with risk of other gynecological cancers, even though the prevalence rate of UL is very high." (PMID 31423418, 2019).
Hearing impairment (1 paper, 2016). A decreased magnitude of the sensory perception of sound. "For example, mutations of several genes involved in oestrogen signalling lead to hearing impairment, such as Esr2, Esrrb and Esrrg in mice and ESRRB in human deafness type DFNB35, and hearing impairment is a feature of oestrogen deficiency in Turner syndrome in humans." (PMID 26881968, 2016).
hemorrhagic stroke (1 paper, 2022). A stroke caused by a bleed on the brain. "ESR2 and COC exposure have synergistic effect in the occurrence of hemorrhagic stroke." (PMID 35413898, 2022).
HIV-1 infection (1 paper, 2022). The type species of lentivirus and the etiologic agent of acquired immunodeficiency syndrome (AIDS). "This compound could use three targets (ESR1, ESR2 and SERPINB9) to regulate MCM2-TUBB2A, of which MCM2 can effectively block HIV-1 infection of macrophages by inhibiting viral DNA synthesis." (PMID 36534703, 2022).
kidney cancer (1 paper, 2021). Primary or metastatic malignant neoplasm involving the kidney. "This is in contrast to the results of the present study, which showed that ESR2 expression was not a risk factor for kidney cancer." (PMID 34322374, 2021).
kidney stone (1 paper, 2023). "Our findings suggest that BSHS may inhibit kidney stone formation mainly by regulating estrogen and estrogen receptor levels, inhibiting oxidative stress processes, reversing apoptosis, and decreasing CaOx crystals deposition through E2/ESR1/ESR2, NRF2/HO-1, and BCL2/BAX signaling pathways." (PMID 36864834, 2023).
Lipoatrophy (1 paper, 2022). Localized loss of fat tissue. "Conversely, the T allele of the estrogen receptor-2 (ESR2) gene was linked with the development of lipoatrophy when contrasted with the reference C allele." (PMID 35628408, 2022).
mental disorder (1 paper, 2021). A disease that has its basis in the disruption of mental process. "Although the fine-mapping of TWAS hits did not support the involvement of ESR2 in the brain, analysis of existing literature points at its role in neurodevelopment and mental disorders." (PMID 34566951, 2021).
oropharyngeal squamous cell carcinoma (1 paper, 2017). "In line with this assumption, ESR2-positive oropharyngeal squamous cell carcinoma (OPSCC) with high SMR3A expression had an unfavorable progression-free and disease-specific survival as compared to those tumors with low SMR3A expression." (PMID 28166815, 2017).